SLCO4A1 (solute carrier organic anion transporter family member 4A1)
Description:
Organic anion antiporter with apparent broad substrate specificity. Recognizes various substrates including thyroid hormones 3,3',5-triiodo-L-thyronine (T3), L-thyroxine (T4) and 3,3',5'-triiodo-L-thyronine (rT3), conjugated steroids such as estrone 3-sulfate and estradiol 17-beta glucuronide, bile acids such as taurocholate and prostanoids such as prostaglandin E2, likely operating in a tissue-specific manner. May be involved in uptake of metabolites from the circulation into organs such as kidney, liver or placenta. Possibly drives the selective transport of thyroid hormones and estrogens coupled to an outward glutamate gradient across the microvillous membrane of the placenta. The transport mechanism, its electrogenicity and potential tissue-specific counterions remain to be elucidated (Probable).
Synonyms: OATP4A1; OATPRP1; POAT; OATP-E; OATPE; SLC21A12
Tractability: Antibody: UniProt places it where antibodies can reach, with high confidence; its Gene Ontology location is reachable by antibodies, with high confidence; UniProt predicts a signal peptide or a membrane-spanning region. PROTAC: ubiquitination databases record sites on it.
Target class: Electrochemical transporter; SLC superfamily of solute carriers; SLC21/SLCO family of organic anion transporting polypeptides; Transporter
Gene: Protein-coding gene on chromosome 20 (62,642,440 to 62,685,785, forward strand). Ensembl gene ENSG00000101187.
Subcellular location: Cell membrane
Subcellular location (Human Protein Atlas): Cell Junctions
Pathways (Reactome):
Transport of small molecules: Organic anion transport by SLCO transporters
Gene Ontology:
Molecular function: prostaglandin transmembrane transporter activity; protein binding; transmembrane transporter activity; thyroid hormone transmembrane transporter activity
Biological process: sodium-independent organic anion transport; prostaglandin transport; thyroid hormone transport; transmembrane transport
Cellular component: cell junction; basolateral plasma membrane; plasma membrane; membrane
Genetic constraint (gnomAD): Loss-of-function variants: 53 observed, 62.94 expected, observed/expected ratio (o/e) 0.84, 90% interval 0.67 to 1.06. The upper end of that interval is the gene's LOEUF score, 1.06, which puts it in group 4 of 6, group 1 being the genes least tolerant of losing a copy. Missense variants: 919 observed, 940.98 expected, observed/expected ratio (o/e) 0.98, 90% interval 0.92 to 1.03. Synonymous variants: 471 observed, 424.18 expected, observed/expected ratio (o/e) 1.11, 90% interval 1.03 to 1.2.
Homologues: Orthologues: chimpanzee SLCO4A1 (99% identical), macaque SLCO4A1 (94% identical), dog SLCO4A1 (79% identical), pig SLCO4A1 (77% identical), mouse Slco4a1 (75% identical), rat Slco4a1 (74% identical), guinea pig SLCO4A1 (73% identical), zebrafish slco4a1 (59% identical), tropical clawed frog slco4a1 (58% identical), Drosophila melanogaster Oatp26F (40% identical), Caenorhabditis elegans Y70G10A.3 (32% identical), Caenorhabditis elegans F53B1.8 (31% identical), and 1 more. Paralogues in human: SLCO4C1 (39% identical), SLCO5A1 (34% identical), SLCO6A1 (28% identical), SLCO3A1 (27% identical), SLCO1C1 (26% identical), SLCO2B1 (26% identical), SLCO2A1 (25% identical), SLCO1B3 (24% identical), SLCO1B1 (24% identical), SLCO1A2 (23% identical).
Diseases named in the same sentence as SLCO4A1 in open-access papers:
SLCO4A1 is named in the same sentence as 29 diseases in open-access papers, as found by Europe PMC text mining. Sharing a sentence is not in itself a finding about the gene and the disease. The quoted sentences say what the papers report.
colorectal cancer (4 papers, 2006 to 2023). A primary or metastatic malignant neoplasm that affects the colon or rectum. "SLCO4A1 was highly expressed in colorectal cancer (including COAD and READ) compared with the corresponding normal tissues." (PMID 37124063, 2023). "SLCO4A1 is proved to be highly expressed in colorectal cancer and affect prognosis, but its role in NB has not been studied." (PMID 36713522, 2022). "Among the up-regulated genes in colorectal cancer, we found 14 genes involved in signal transduction (TDGF1 and ENC1), transcription (SOX9, MYC, and HGFR/MET), nuclear transport (NUP62, NUPL1, NUP155, KPNA2, RANBP5, CSE1L/CAS, NTF2, and RANBP1) and cellular transport (SLCO4A1)." (PMID 16919171, 2006).
colon cancer (3 papers, 2022 to 2025). "In colon cancer cells, SLCO4A1 is markedly upregulated, along with elevated expression of its antisense RNA (SLCO4A1-as1)." (PMID 40710326, 2025). "Interactions of SLCO4A1, miR-150-3p, and SLCO4A1-AS1 have been investigated in colon cancer tissues." (PMID 38094755, 2023).
lung carcinoma (3 papers, 2010 to 2021). "PTK2, PGF, SLCO4A1 and Cdc27 are among the genes in Merged-module whose over-expression has been reported in different cancers including lung cancer and we have shown it as well." (PMID 23874428, 2013).
neuroblastoma (3 papers, 2016 to 2022). Neuroblastoma (NB) is the most common solid, extracranial childhood tumor. "Since putative hypoxia-inducible (factor HIF)-1 transcription factor binding sites were identified in the SLCO4A1 promotor, hypoxia may cause an upregulation of SLCO4A1, which was observed in neuroblastoma and for other SLCOs in colon and pancreatic cancer." (PMID 36105223, 2022).
ovarian carcinoma (3 papers, 2018 to 2022). A malignant neoplasm originating from the surface ovarian epithelium. "We also examined the SLCO4A1 encoded OATP4A1 in the ovarian cancer cell lines by Western blotting and showed OATP4A1 immunoreactive protein in ovarian cancer samples by IHC and double-IF staining." (PMID 36105223, 2022). "In the group of ovarian cancer cells with low SLCO4A1 levels, SLC25A12 coding for the SLC25A12 transporter was identified among the most significant enriched genes." (PMID 36105223, 2022). "Different from the four SLCO genes (SLCO3A1, 2A1, and 2B1) with high expression in mesothelial cells, we identified SLCO4A1 having higher levels in a group of ovarian cancer cell lines compared with mesothelial cells." (PMID 36105223, 2022). "Surprisingly, for the ovarian cancer cell group with high SLCO4A1, the overall pattern for the genes was similar to that of mesothelial cells." (PMID 36105223, 2022). "Group 2 with significantly higher levels (p = 0.005) of SLCO4A1 (median: 412 read counts) includes the remaining 18 ovarian cancer cell lines from 14 patients and the 5 mesothelial cell lines, the latter with SLCO4A1 levels of 41 read counts (median)." (PMID 36105223, 2022). "Among the SLCO family, SLCO4A1 is of particular interest, as it is highly expressed in ovarian cancer." (PMID 36105223, 2022). "Spearman correlation analysis of individual genes indicated that ABCC3, an efflux pump from the family of multidrug resistance-related transporters, has a strong and significant positive correlation to SLCO4A1 in the ovarian cancer cells (r = 0.75, p < 0.001)." (PMID 36105223, 2022). "The current study aimed at elucidating the expression of SLCO4A1 in patient-derived ovarian cancer cell lines." (PMID 36105223, 2022). "Group 1 with lower levels of SLCO4A1 consists of 15 ovarian cancer cell lines from nine patients (median SLCO4A1 levels: 72 read count)." (PMID 36105223, 2022). "To elucidate SLCO4A1 expression and to establish a possible association between the transporter und cellular signalling pathways in HGSOC, we used 33 patient-derived ovarian cancer cell lines which were demonstrated to reflect the pattern of genes expressed in tumors from individual patients." (PMID 36105223, 2022). "Notably, ubiquitously expressed SLCO2A1, SLCO2B1, SLCO3A1, and SLCO4A1 genes have been identified in ovarian cancer." (PMID 30131693, 2018). "In addition, the expression of SLCO4A1 is strongly increased in ovarian cancers." (PMID 33958701, 2021). "Therefore, these pathways are rather unlikely to be related to SLCO4A1 in the ovarian cancer cell lines." (PMID 36105223, 2022).
inflammatory bowel disease (2 papers, 2020 to 2022). A spectrum of small and large bowel inflammatory diseases of unknown etiology. "For example, in colon of patients with inflammatory bowel disease, the mRNA expression levels of SLCO4A1, and also other SLCOs, e.g., SLCO2B1 were upregulated, while the expression of transporters from other families was downregulated." (PMID 36105223, 2022).
pancreatic cancer (2 papers, 2022 to 2023). "In addition, SLCO4A1 has been found to be overexpressed in pancreatic cancer and is expected to be an important biomarker for targeted therapy of pancreatic cancer." (PMID 37124063, 2023).
colon adenocarcinoma (1 paper, 2023). "However, the association of SLCO4A1 with prognosis and tumor immune infiltration in colon adenocarcinoma (COAD) remains indistinct." (PMID 37124063, 2023).
Graves' hyperthyroidism (1 paper, 2023). "The genes related to the antithyroid effects of long-term iodine loading are Slc5a5, Slc26a4, Duox2, and Duoxa2, in addition to Tpo, Dio1, and Slco4a1, which are upregulated in Graves' hyperthyroidism." (PMID 36565031, 2023). "However, our RNA-seq analysis showed that the gene expression of Slco4a1, which is also known as organic anion transporting polypeptide (OATP) 4A1, was increased in Graves' hyperthyroidism and decreased with long-term inorganic loading." (PMID 36565031, 2023).
ischemic stroke (1 paper, 2024). A stroke disorder caused by obstruction of blood flow to the brain, due to thrombotic (local blood clot formation) or embolic (due to a blood clot or other material traveling from another site) event. "While both Slco4a1 and Slc6a6 are known targets of NFAT5, the latter may in fact influence the outcome of ischemic stroke by regulating the transport of the neuroprotective endogenous amino acid taurine through the BBB." (PMID 39710754, 2024).
low grade glioma (1 paper, 2022). A grade I or grade II glioma arising from the central nervous system. "Gene expression-based survival analysis showed that six from seven detected highly m6A modified lncRNAs (PVT1, SLCO4A1, HRAT92, AGAP2-AS1, CEROX1 and ENSG00000262223 had an impact on the prognosis of low-grade glioma (LGG) and GBM (FDR adj." (PMID 35361860, 2022).
mucinous adenocarcinoma (1 paper, 2023). An invasive adenocarcinoma composed of malignant glandular cells which contain intracytoplasmic mucin. "Mucinous adenocarcinoma presented with higher SLCO4A1 expression than adenocarcinoma in patients with COAD." (PMID 37124063, 2023).
prostate carcinoma (1 paper, 2023). A carcinoma that arises from epithelial cells of the prostate gland. "Overexpression of the SLCO4A1 gene in prostate cancer and thyroid cancer indicated a poor prognosis." (PMID 37124063, 2023).
pulmonary fibrosis (1 paper, 2023). Chronic progressive interstitial lung disorder characterized by the replacement of the lung tissue by connective tissue, leading to progressive dyspnea, respiratory failure, or right heart failure. "To further verify the differential expression of candidate hub genes between IPF and control samples, we then established a bleomycin-induced pulmonary fibrosis mouse model and detected the expression of SLCO4A1, ASPN and SFRP2 between fibrotic lung samples and control samples from model mice." (PMID 37334348, 2023).
retinal detachment (1 paper, 2011). An eye emergency condition which may lead to blindness if left untreated. "Within the genes identified, the expression of the major histocompatibility complex I gene HLA-C enables diagnosis of the disease, while PKD2L1 and SLCO4A1 -which are both down-regulated- act synergistically to provide an estimate of the duration of the retinal detachment process." (PMID 22174898, 2011).
viral infections (1 paper, 2020). "Both SLCO4A1 and VRD have been reported to be part of the RNA response to bacterial or viral infections." (PMID 32973863, 2020).
cancer (10 papers, 2013 to 2023). A tumor composed of atypical neoplastic, often pleomorphic cells that invade other tissues. "SLCO4A1, a potential biomarker for various cancers, is involved in neutrophil-mediated immune responses." (PMID 36814903, 2023). "Previous studies have shown that SLCO4A1 promotes tumorigenesis and the progression of different carcinomas, but the relationship between SLCO4A1 and fibrosis has rarely been reported." (PMID 37334348, 2023). "By comparing levels of SLCO4A1 with a panel of genes, selected for their role in the regulation of biotransformation, cell proliferation and tumor progression, we identified two groups of cancer cell lines, one with high SLCO4A1 and the other with low SLCO41 levels." (PMID 36105223, 2022). "Additionally, studies on SLCO4A1 have been predominantly focused on microRNA and cancer." (PMID 35711567, 2022). "The data indicated that all analyzed SLCO genes exhibited significantly increased expression levels (and/or were more often detectable) in cancer compared with benign tissue samples (FDR ranging from 0.038 for SLCO2B1 to 5.3 × 10−12 for SLCO3A1 and SLCO4A1, respectively)." (PMID 30131693, 2018). "In addition to the regulation of SLCO4A1 through pathological alterations such as metabolic changes with ROS production and inflammation, SLCO4A1/OATP4A1 expression may also change cancer cell metabolism and cell fate by its transport function for endogenous substrates." (PMID 36105223, 2022).
tumor (8 papers, 2012 to 2023). "Another major result of our study was that the expression of SLCO4A1 was associated with multiple tumor-infiltrating immune cells and abundant immune molecules." (PMID 37124063, 2023). "Our study clearly showed that SLCO4A1 was closely linked to tumor immune infiltration in COAD and might be a new molecular target, which was worth further exploration." (PMID 37124063, 2023). "The correlation of the expression level of SLCO4A1 with tumor immune infiltration in COAD was investigated using the TIMER database." (PMID 37124063, 2023). "In our study, we found that SLCO4A1 played an important role in the prognosis and tumor immune infiltration in COAD." (PMID 37124063, 2023). "At present, the biological role of SLCO4A1, its prognostic value, and the relationship of SLCO4A1 with tumor immune infiltration in COAD are still unclear." (PMID 37124063, 2023). "By IHC staining, we showed that SLCO4A1/OATP4A1 in FFPE samples reflects the SLCO4A1 expression in the tumor cell lines derived from the tumor of the same patient." (PMID 36105223, 2022). "Via gene expression, overall survival (OS), disease free survival (DFS) of TCGA database, INHBA and SLCO4A1 were found overexpressed in tumor tissues and significantly OS-/DFS- differential." (PMID 34476008, 2021). "Moreover, our study also explored the correlation between the expression of SLCO4A1 and tumor immune infiltration in COAD." (PMID 37124063, 2023). "Therefore, we can better predict the prognosis of COAD and evaluate the status of tumor immune infiltration by testing the expression level of SLCO4A1 in COAD." (PMID 37124063, 2023). "In addition, the relationship of SLCO4A1 with tumor immune infiltration in COAD was verified via TIMER and TISIDB databases." (PMID 37124063, 2023). "Firstly, the relationship between SLCO4A1 expression level and the abundance of tumor infiltrating lymphocytes was explored to identify which types of TIICs could be regulated by SLCO4A1 gene." (PMID 37124063, 2023). "In addition, the expression level of the SLCO4A1 protein was elevated in COAD tumor tissues obtained from the Human Protein Atlas." (PMID 37124063, 2023). "Our study suggested that SLCO4A1 could be a valuable biomarker for evaluating prognosis and tumor immune infiltration in COAD patients." (PMID 37124063, 2023). "In addition, the correlation between SLCO4A1 and tumor immune infiltration was studied by using TIMER and TISIDB databases." (PMID 37124063, 2023). "In addition, we need to further explore the role of SLCO4A1 in regulating tumor immune infiltration in COAD." (PMID 37124063, 2023). "This study showed that BIRC5, SLCO4A1, POPDC3, and HK2 were significantly downregulated in stage MS NB and affected the survival rate of children, indicating that the low expression of these four genes is a factor conducive to tumor regression." (PMID 36713522, 2022).
SLCO4A1 also shares sentences with these, for which no sentence is quoted: breast carcinoma (2 papers); gastric cancer (2); adenocarcinoma (1); idiopathic pulmonary fibrosis (1); Infertility (1); intrahepatic cholestasis (1); intrauterine growth restriction (1); liver cancer (1); polycystic ovarian syndrome (1); serous ovarian cancer (1); thyroid cancer (1).